AR (androgen receptor)
Diseases named in the same sentence as AR in open-access papers (continued):
Sharing a sentence is not in itself a finding about the gene and the disease.
cancer (continued). "In addition, AR signaling persists in normal and malignant prostatic cells except for when AR antagonism triggers the transition to highly glycolytic AR-indifferent carcinoma." (PMID 33163409, 2020). "Preclinical studies have suggested a direct connection between the AKT which is a target for many anti-cancer agents and AR signaling cascade, showing a dynamic interplay between these pathways during the development of ADT resistance and the development of androgen insensitivity." (PMID 31136301, 2019). "A prominent example is enzalutamide (Xtandi®), a second-generation AR antagonist showing robust anti-cancer activity with an expanding application to patient care for both castration-resistant prostate cancer (CRPC) and hormone sensitive prostate cancer (HSPC)." (PMID 31501863, 2019). "In addition to expected increased AR pathway activity in primary PCa, AR pathway activity was also increased in cancer-adjacent and hyperplastic prostate tissue, which is likely caused by elevated local androgen levels." (PMID 30733525, 2019). "Therefore, we diagnosed the five tiny nodules as lung metastases from docetaxel-resistant CRPC with few AR-signaling-dependent cancer cells." (PMID 31185946, 2019). "In cancers, this ratio is extremely skewed: more than 99% of the cancer mass is a luminal-like cell, which is incompletely differentiated (whilst expressing androgen receptor and prostate-specific antigen) but has gained the ability to replicate in an uncontrolled fashion." (PMID 31108832, 2019). "In FMCs, positive immunohistochemical staining for AR was most commonly nuclear, and was observed in neoplastic cells as well as scarce stromal cells including endothelial cells and cancer-associated fibroblasts (data not shown)." (PMID 31888566, 2019). "This cancer is often characterized by a slow and symptom-free growth, and early-stage treatments include radical prostatectomy, novel androgen receptor (AR) pathway inhibitors, such as abiraterone and enzalutamide, external beam radiotherapy (RT), brachytherapy and cryotherapy." (PMID 31174415, 2019). "Interestingly, a superficial reanalysis of the individual patient samples from the Pomerantz cohort shows that in every case, FOX and HOX motifs are more enriched in the AR peaks from cancer specimens than in the matched normal samples." (PMID 31520575, 2019). "Importantly, TGF-β signaling and microRNA-mediated regulation of gene expression often act in complicated feedback circuits that involve other crucial regulators of cancer progression (e.g., androgen receptor)." (PMID 31842336, 2019). "Considering our findings and those of other studies that support a relevant role of the GR in this type of cancer, it would be useful to revisit the relevance of the expression profile of nuclear receptors (AR, MR, VDR, TDR, etc.), coactivators, corepressors and isoforms." (PMID 30987626, 2019). "The analysis revealed that AR was enriched in cancer-related pathways." (PMID 31413736, 2019). "Other TNBC subtypes also express AR and utilize AR signaling for cancer cell survival." (PMID 31527644, 2019). "AR overexpression (found in 33 cases/180, 18%) and FOXA1 index ≥1% (64/180, 36%) were associated with a longer disease-free interval, overall survival, and cancer-specific survival in cats with FMC." (PMID 31888566, 2019). "Additionally, growth hormones such as epidermal growth factor (EGF) increase TIF2/GRIP1 coactivation of androgen receptor activity in recurrent cancer cells." (PMID 31552182, 2019). "On the other hand, enhanced AR signaling pathway could play an important role in cancer initiation and progression in vitro and in vivo." (PMID 30961575, 2019).
cancer (continued). "Recently, androgen regulated BRDs such as BRD2 and ATAD2 increased chromatin accessibility with enhancing AR recruitment to chromatin, which may drive cancer progression." (PMID 31527644, 2019). "To begin to understand what affect the differences in AR binding have on benign and cancerous prostate epithelial cells, we identified AR peaks that were unique to benign and cancer tissue from our patients and created lists of putative ‘peak‐associated genes’." (PMID 31520575, 2019). "Tumors in the dataset were divided into four subgroups (luminal-androgen receptor expressing, basal, claudin-low and claudin-high), using the cancer stem cell hypothesis as reference." (PMID 30733547, 2019). "An example locus that includes cancer-specific enhancer–promoter loops is the AR locus." (PMID 31515496, 2019). "Mimicking the cancer stem cell hypothesis, we established the following workflow: Samples with high luminal metanode activity were classified as the luminal androgen receptor group (LAR)." (PMID 30733547, 2019). "ER stress and enhanced autophagy in response to hepsin overexpression were not limited to the PC-3 cell line with all its cancer-specific peculiarities, but also occurred in AR-positive LNCaP PCa and in HEK293 cells, which demonstrates generalizability of our findings." (PMID 31399560, 2019). "Immunohistochemistry data on both SNW1 and AR were available from 6984 cancers." (PMID 31043167, 2019). "Estrogen receptor α and androgen receptor are widely recognized as oncogenes, while other NRs, such as proliferator-activated receptor γ, may have inhibitory functions on cancer proliferation." (PMID 30867652, 2019). "IHC data on both GSK3ß and AR were available from 6,253 cancers." (PMID 30899444, 2019). "Future development of drug candidates inhibiting TOX–DNA interactions could follow previous studies where SMIs have been successfully developed via CADD to target the DNA-binding domains of other cancer drug targets, such as AR, ERG, and MYC." (PMID 31554191, 2019). "Re‐expression of AR in PC3 cells may have a potential to reduce the stemness characteristics of these cancer cells." (PMID 30206982, 2019). "Most of the carcinomas (97%) contained AR-positive neoplastic cells." (PMID 31888566, 2019). "In a low-androgen environment, aberrant activation between cancer cells and stromal cells may be an important mechanism controlling AR activity and AR-regulated PSA expression." (PMID 29614830, 2018). "In contrast, AR is highly expressed in HER2-positive or ESR1/PGR-positive cancers (> 95%)." (PMID 30279965, 2018). "The death of cancer cells caused by fibroblasts has been reported by others, but not in the context of myofibroblast AR." (PMID 29721186, 2018). "This cancer is highly dependent on the androgen receptor (AR) signaling pathway." (PMID 29416632, 2018). "Down-regulated genes were enriched in the AR pathway, T cell response, and cancer B cell response." (PMID 29912871, 2018). "We found that selinexor significantly inhibited the proliferation of 22Rv1 and VCaP cells, suggesting that the anti-cancer activity of SINE could be mediated through the down-regulation of AR/ARv signaling." (PMID 30450161, 2018). "Although these QNBC tumors would probably not respond to anti-AR based therapeutics, the 20-30% of TNBC cancers that do in fact express AR might and most likely belong to the LAR molecular subgroup." (PMID 30279965, 2018). "Collectively, these findings raise the question whether a minimum level of AR activity may be required for baseline expression of SRARP in AR+ cancer cells, while higher levels of AR activity suppress this gene." (PMID 29577611, 2018). "Moreover, as the disease evolves from androgen-sensitive cancer to castration-resistant prostate cancer (CRPC), the growth of cancer cells still rely on AR signaling axis." (PMID 30555332, 2018).
cancer (continued). "Indeed, we found that SINE in vitro and in vivo potentiated the anti-cancer activity of anti-AR agents, enzalutamide and abiraterone, by inhibition of XPO1 and AR splice variants." (PMID 30450161, 2018). "In addition to MITF, another key cancer driver that is regulated by lysine modification is the androgen receptor (AR)." (PMID 30065750, 2018). "In addition, there were multiple genes induced that are involved with cell and organelle structure and function (PNCK, UBD, CDH2, HERC5) and importantly, genes associated with the prostate, AR (MMP7, CDH2, ENO2, IGFBP3) and cancer (IFIT3, IFI44L)." (PMID 29416764, 2018). "Nevertheless, the mechanisms by which androgen and AR influence cancer cell growth are complex." (PMID 29716628, 2018). "Thus, AR signaling remains active in PCa cells and aids in its survival under low levels of circulating androgens and additionally allows the cancer cells to manipulate the bone microenvironment to fuel its growth." (PMID 29967592, 2018). "However, over time, the cancer cells adapt undergo selection to proliferate and survive under low levels of circulating androgens by upregulating AR and becoming unresponsive to ADT." (PMID 29967592, 2018). "Overall, these results support the hypothesis that inhibition of multiple DUBs in PCa (either with BA or WP) reduces AR expression and increases cancer-specific cell death." (PMID 30177856, 2018). "AR signaling interferes with the normal development and function of the target tissues, and may induce pathological conditions, including cancers." (PMID 29108248, 2017). "This could mean that through the high AR level and different expression profile of AR compared to favorable prognosis, younger patients have even more aggressive type of cancer than patients in more advanced age." (PMID 29206234, 2017). "However, AMACR+ benign luminal cells (n = 508) showed similar AR expression as AMACR+ cancer cells (0.113 vs. 0.112, p = 0.191)." (PMID 29138507, 2017). "Thus, in both PCa and BCa, AR signaling appears to regulate distinct sets of target genes in hormone-dependent cancers (i.e., hormone-naïve PCa, ER+ BCa) and hormone-refractory cancers (i.e., CRPC, ER− BCa, hormone therapy-resistant ER+ BCa)." (PMID 28134791, 2017). "More recently, infiltrating CD4+T cells could promote tumor metastasis by enhancing cancer cell invasion via modulation of FGF11/miRNA-541/AR/MMP9 signaling." (PMID 29197379, 2017). "Furthermore, inhibiting the AR chaperone, HSP90, in CAFs, thereby reducing the AR activity, retards growth of patient derived cancer cell and CAF recombinant xenografts in mice." (PMID 28117763, 2017). "Importantly, multivariate Cox regression analyses revealed that AR is an independent prognostic factor for cancer-specific survival." (PMID 29108248, 2017). "Androgen receptor is an important regulator of prostate development and cancer." (PMID 28112153, 2017). "The pleiotropic effects of AR-signaling raise the specter that targeting this pathway may have beneficial effects in a number of different cancers." (PMID 28085048, 2017). "It is known that AR signalling plays a role in regulating cancer cell proliferation and apoptosis." (PMID 28415597, 2017). "In conclusion, our results show that improved anti-cancer efficacy can be achieved by co-targeting the AR axis and fat oxidation via CPT1A, which may have clinical implications, especially in the mCRPC setting." (PMID 28915573, 2017). "As a cytochrome P450 17A1 (CYP17A1) inhibitor, abiraterone impedes the production of androgens in adrenal glands, cancer cells and other sources, whilst enzalutamide directly binds to the AR and blocks nuclear translocation and activation of downstream AR-related pathways." (PMID 28241429, 2017). "TFF3 also may contribute to cancer metastasis with epithelial-to-mesenchymal transition (EMT) potentially through the regulation of genes such as androgen receptor (AR), FOXA1 and human epidermal growth factor receptor-type 2 (HER2)." (PMID 28070169, 2017).
cancer (continued). "AR (androgen receptor), a target gene of hsa-miR-3148, was enriched in pathways in cancer." (PMID 28904974, 2017). "Thus, the present results are in line with literature reports, which show that AR levels increase slightly in cancer progression in TRAMP mice from 8 to 22 weeks of age." (PMID 28499383, 2017). "Androgen signals through androgen receptor (AR) to influence prostate development and cancer." (PMID 28112153, 2017). "This shows that the AR has a dominant role in promoting proliferation of cancer cells." (PMID 28499383, 2017). "Since the SD range in consideration with mean value was relatively wider in ER-negative than in ER-positive tumors, and most samples with high AR mRNA levels exhibited high FOXA1 expression in ER-positive cancers; therefore, the correlation coefficient was higher in ER-negative tumors." (PMID 29137314, 2017). "Interestingly, HER2, PAX2, AHR, AR, and RUNX factors have each been implicated in cancer stem cell biology (and see “Discussion”)." (PMID 28412963, 2017). "Additionally, tamoxifen-resistant cancers in which AR is present tend to have both higher levels of AR expression and in one study, higher AR to ER nuclear expression." (PMID 28245550, 2017). "Whereas PAs are AR-positive in 30% of the cases, 90% of carcinoma ex-PAs express AR." (PMID 28208703, 2017). "Notably low AR expression was more often encountered in carcinomas with established distant metastasis." (PMID 29108248, 2017). "For example, percentage of AR-positive tumors was 46% in pT1 compared to 28% in pT3 carcinomas." (PMID 29108248, 2017). "Some TNBC patients, e.g. luminal androgen receptor or molecular apocrine cancers, may have better prognosis than the remaining majority." (PMID 26930401, 2016). "Additionally, activation of the AR is required for survival of benign luminal epithelial cells and primary cancer cells, thus androgen deprivation therapy (ADT) leads to apoptosis in both benign and cancerous tissue." (PMID 27378372, 2016). "Indeed, the importance of the AR in regulating stem cell plasticity is evident by its conserved role across embryonic and somatic stem cells, in addition to cancer stem cells." (PMID 26880966, 2016). "However, a few reports have identified a subset of cancers where AR expression is directly proportional to Ki67 staining and correlates with poorer OS and DFS." (PMID 27918430, 2016). "As one of the phytoestrogens due to its polyphenolic structure, kaempferol also exerts anti-proliferative and anti-carcinogenic actions though ER, AR, the aryl hydrocarbon receptor (AhR) and the progesterone receptor (PR) signaling pathways in many types of cancer." (PMID 27231938, 2016). "Increased levels of normal DNA could reduce our ability to detect AR CN gain clones and thus, reduce the difference we observed between AR gain and normal cancers." (PMID 27191887, 2016). "In addition, PD-L1 positivity in cancer cells significantly predicted AR expression on ≥1% of cancer cells (OR= 2.6; 95% CI 1.1–6.1)." (PMID 28721372, 2016). "Notably, it has been reported that relative to low-grade PC, high-grade cancer shows an attenuated androgen signaling signature that is similar to metastatic PC, and decreased expression of AR-dependent genes was observed during PC progression." (PMID 27221037, 2016). "Similar to other LDB-lacking AR variants, type 3a AR transcripts are expressed at a level of <5% of the wild-type AR in normal breast and prostate tissues and in the cancer cell lines studied here." (PMID 28035996, 2016).
cancer (continued). "We demonstrate that suppression of androgen receptor (AR), cullin-associated and neddylation-dissociated 1 protein (Cand1), and unknown PS1145 targets sensitize cancer cells to CRL inhibition." (PMID 27906189, 2016). "AR is central to growth and survival of both benign and malignant prostate epithelial cells, but the mechanisms seem to be very different in normal prostate homeostasis and cancer growth." (PMID 27378372, 2016). "Thus, our findings revealed a new sight of androgen/AR role in hepatocarcinogenesis through affecting cancer cells stemness and provided evidence for this axis suppression in HCC therapy." (PMID 27167111, 2016). "We show that miR-203 can be activated by AR and subsequently suppress cancer progression." (PMID 27028864, 2016). "We also investigated the effects that AR has on cancer cell migration." (PMID 27340775, 2016). "Although neuroendocrine differentiation and cancer stem cell pathways may bypass AR, alterations in the androgen signaling pathway are still considered a predominant factor in mediating the emergence of resistance to androgen deprivation therapy in PCa." (PMID 27611945, 2016). "Because of the critical role of ubiquitination pathway on the activation of both AR and AKT, an ubiquitylome mapping may provide some clues on mechanisms of the reciprocal regulation of PI3K/AKT and AR signaling in PTEN-deficient cancers." (PMID 25734985, 2015). "Furthermore, although there are many possible gene targets, we focused our attention on genes known to be targets of AR in cancer cells and play a role in placental processes such as proliferation, migration and angiogenesis." (PMID 25675430, 2015). "It is conceivable that interrogation of androgen receptor positivity and treatment with androgen antagonistic agents could therefore be an effective strategy in these cancers." (PMID 25595907, 2015). "The therapeutic effect of second generation anti-androgens such as enzalutamide and abiraterone acetate implies most cancer cells, which still express functional AR, require AR signaling to evade traditional regulatory mechanisms to survive androgen deprivation strategies." (PMID 26121643, 2015). "AR-mediated gene regulation of potential txr genes may be less important in advanced cancer cells in which stable ABCB1 amplification is dominantly responsible for the multidrug resistance phenotype." (PMID 26318424, 2015). "Importantly, Sp1 is elevated in many cancers and studies using LNCaP cells show that this leads to increased AR transcription." (PMID 26448047, 2015). "Although the underlying mechanism remains unknown, it has been recently suggested that DHRS7 may promote de novo androgen synthesis, thus directly influencing the activation of the AR, thereby stimulating cancer progression." (PMID 26311046, 2015). "In addition, strategies addressing systemic treatments with a lower toxicity profile such as therapeutic cancer vaccines or novel class of androgen receptor inhibitors substituting partly ADT should be investigated." (PMID 26577452, 2015). "Thus, androgen-deprivation therapy strives to perturb AR activity and complements conventional cancer therapies, such as radical prostatectomy, radio- or chemotherapy." (PMID 25869206, 2015). "To investigate the role of stromal AR in cancer, we utilized in vivo tissue recombination." (PMID 25965833, 2015). "In their 2013 Cancer Cell paper, Sharma and colleagues (2013) used chromatin immunoprecipitation sequencing (ChIP-seq) to identify genome-wide binding targets of AR in prostate tissue from patients with CRPC, ADT-responsive PC, or untreated PC, compared with benign prostate hyperplasia." (PMID 26401447, 2015). "The AR itself plays an essential role both in male development and prostate and other cancers." (PMID 26461474, 2015). "Moreover, in cancer cells, CDK5, ERBB2/ERBB3, and beta-catenin have been linked through another member of the beta-catenin network—the androgen receptor (AR)." (PMID 26509276, 2015).